HMGA1 (high mobility group AT-hook 1)
Diseases named in the same sentence as HMGA1 in open-access papers (continued):
Sharing a sentence is not in itself a finding about the gene and the disease.
cancer (continued). "In this article, we discuss the current findings on HMGA1 in tumours as well as recent progress in characterizing the molecular mechanism and function of HMGA1 in the tumourigenesis and malignant progression of numerous cancers." (PMID 30614613, 2019). "In this work we continued this characterization of the oncogenic role of HMGA1 exploring an additional mechanism, i.e., the contribution of HMGA1 to the epigenetic status of cancer cells." (PMID 31382504, 2019). "As HMGA1 is overexpressed in embryonic tissues, comprehending the role of HMGA1 in cancer is essential for our understanding of HMGA1‐mediated tumourigenesis." (PMID 30614613, 2019). "Through analysis of the molecular mechanism of HMGA1 and clinical studies, emerging evidence indicates that HMGA1 promotes the occurrence and metastasis of cancer." (PMID 30614613, 2019). "HMGA1 was previously reported to frequently over-express in NSCLC tissues and to be associated with the metastatic progression of cancer cells." (PMID 30390627, 2018). "As a member of the HMGA protein family, HMGA1 also has been reported to be overexpressed in cancers and promote tumorigenesis." (PMID 29416690, 2018). "Tumours and cancer cell lines express at least one type of HMGA proteins (HMGA1 or HMGA2) and show a high level of oncogenic transformation." (PMID 29853899, 2018). "Poorer prognosis is due to the fact that HMGA1 promotes the transcription of many genes involved in tumor growth, invasion, migration, neoangiogenesis, epithelial-mesenchymal transition and cancer metastasis." (PMID 30034366, 2018). "Several studies showed that overexpression of HMGA1 drives neoplastic transformation in cultured cells, whereas suppression of HMGA1 expression inhibits oncogenic and cancer stem cell properties." (PMID 30071685, 2018). "We have developed the strategy of introducing decoy hyper binding sites for HMGA1 into the nucleus of cancer cells with the goal of competetively sequestering overexpressed HMGA1 and thus suppressing its oncogenic action." (PMID 29462157, 2018). "In some of these cancers, HMGA1 expression strongly correlates with an advanced stage, the metastatic potential and reduced survival." (PMID 30034366, 2018). "HMGA1 pseudogenes were found overexpressed in several human carcinomas, and their expression levels positively correlate with an advanced cancer stage and a poor prognosis." (PMID 29149041, 2017). "Given its dual role in normal development and cancer, further studies to dissect HMGA1 function in each setting are needed to determine the therapeutic potential of targeting HMGA1 in cancer or harnessing its function for tissue regeneration." (PMID 28452345, 2017). "Emerging evidences have demonstrated that HMGA1 is a promising therapeutic target for multiple cancer types." (PMID 28290473, 2017). "The high-mobility group (HMG)A family of proteins has four members; one of these, HMGA1, plays a critical role in cancer progression, development, and metabolism, among others." (PMID 28255749, 2017). "HMGA1 belongs to the High Mobility Group A protein family, architectural proteins that are overexpressed in all the malignant tumours and their overexpression is correlated with a poor patient survival." (PMID 29149041, 2017). "IMP2 stabilization of HMGA1 mRNA plus IMP2 stimulated IGF2 production synergistically drive cancer cell proliferation and account for IMP2’s tumor promoting action." (PMID 28753127, 2017). "The HMGA1 oncofetal protein has a prominent role in controlling the expression of an articulated set of genes involved in various aspect of cancer cell transformation." (PMID 28924209, 2017). "HMGA1 expression is high during embryonic development, much lower in adult tissues, but greatly upregulated in a broad range of benign and malignant tumors." (PMID 28753127, 2017). "miR-296-5p has been shown to suppress cancer progression, metastasis, and neo-vascularization by targeting the expression of multiple genes including HMGA1, PUMA and SCRIB." (PMID 29221158, 2017).
cancer (continued). "With the aim of unravelling novel cancer–related mechanisms exploited by HMGA1 we focused our study on secreted proteins (SPs) since they represent an important protein category that has a fundamental role in driving cancer progression." (PMID 28924209, 2017). "Then, the data reported here confirm the oncogenic role of the HMGA1P7 pseudogene that is exerted by the increased expression through a ceRNA mechanism of HMGA1 and other cancer-related genes." (PMID 27874091, 2016). "In this review, we analyze the family of HMGA1 pseudogenes through three aspects: classification, characterization, and their possible function and involvement in cancer." (PMID 26895108, 2016). "These pseudogenes work as competitive endogenous RNA decoys for HMGA1 and other cancer related genes suggesting their role in carcinogenesis." (PMID 27874091, 2016). "Comparative analysis between stably transfected and transiently transfected IL-24 in cancer cells revealed similar effects on HMGA1 expression." (PMID 27602961, 2016). "Future studies need, however, to characterize other genes regulated by the HMGA1 pseudogenes and thereby better define the mechanisms by which they can contribute to cancer progression." (PMID 27874091, 2016). "S100A13 and high mobility group A (HMGA1) are knownto play essential roles in the carcinogenesis and progression of cancer." (PMID 27008379, 2016). "This happens because of shared miRNAs targeting HMGA1P6, HMGA1P7, HMGA1 and other cancer related genes." (PMID 26895108, 2016). "Here, we concentrate our attention on the pseudogenes of the HMGA1 gene, that codes for the HMGA1a and HMGA1b proteins having a critical role in development and cancer progression." (PMID 26895108, 2016). "Studies have shown that HMGA1 primarily mediates cancer progression through PI3K-AKT signaling, which plays a significant role in tumor growth, survival, metastasis, and therapy resistance." (PMID 27602961, 2016). "It is known that the high expression of HMGA1 in cancer cells needs a close cooperation between SP1 family elements and AP1 proteins, stimulated by the activation of Ras GTPase cascade." (PMID 26895108, 2016). "The HMGA1 architectural transcription factor is an oncogene overexpressed in the vast majority of human cancers." (PMID 27723831, 2016). "In vitro and in vivo studies have shown that inhibiting HMGA1 expression with antisense oligonucleotide reduced cancer cell invasion/migration and increased apoptotic cell death." (PMID 27602961, 2016). "We have recently identified two pseudogenes, HMGA1P6 and HMGA1P7 for the HMGA1 gene whose overexpression has a critical role in cancer progression." (PMID 27874091, 2016). "Most importantly, AKT has been reported as the main downstream target of HMGA1 and has been shown to be positively regulated by HMGA1 overexpression in cancer cells." (PMID 27602961, 2016). "Studies have demonstrated that HMGA1 overexpression activates AKT and its associated function in cancer cells." (PMID 27602961, 2016). "Herein we identify the nonhistone architectural nuclear proteins High Mobility Group A1 (HMGA1), whose overexpression is a feature of several human malignancies and has a key role in cancer progression, as transcriptional regulators of SAC genes expression." (PMID 26009897, 2015). "HMGA1 functions in tumor progression by reprogramming differentiated cells into poorly differentiated, stem-like cancer cells." (PMID 25572132, 2015). "Apart from its significant expression during development, HMGA1 is over-expressed in virtually every cancer, where HMGA1 expression levels correlate with tumor malignancy." (PMID 26117853, 2015). "Due to its reliably high expression in almost every type of malignant tumor, HMGA1 is increasingly put forward as a novel marker for medical prognosis." (PMID 26117853, 2015). "HMGA1 is previously demonstrated to be involved in angiogenesis and cancer progression and is upregulated in response to hypoxia." (PMID 25860936, 2015).
cancer (continued). "Remarkably, HMGA1 proteins are over-expressed in virtually every type of cancer, where their expression levels correlate with tumor malignancy and a poor outcome for patients suffering from that particular type of tumor." (PMID 26117853, 2015). "Recent studies provide evidence for HMGA1 being a driving force during cancer growth and tumor progression." (PMID 26117853, 2015). "HMGA1 is found to be overexpressed in almost all aggressive cancers and high levels of HMGA1 point to a poor prognosis in diverse types of tumors." (PMID 25572132, 2015). "A strong decrease of let-7 expression levels has been associated with an aberrant overexpression of HMGA1 and HMGA2 in several human highly malignant carcinomas." (PMID 25859543, 2015). "Silencing HMGA1 expression in invasive, aggressive cancer cells dramatically arrests cell growth and blocks their oncogenic properties, including proliferation, migration, invasion, and orthotopic tumorigenesis." (PMID 25366846, 2014). "Taken together, these results indicate that HMGA1P6, HMGA1P7 and HMGA1 expression is correlated with cancer aggressiveness." (PMID 25268743, 2014). "HMGA1 was localized primarily in the nuclei of PCa cells in cancer foci, with only weak cytoplasmic staining in stromal cells." (PMID 24837491, 2014). "Lastly, the expression of the HMGA1 pseudogenes was significantly correlated with HMGA1 protein levels thereby implicating HMGA1P overexpression in cancer progression." (PMID 25268743, 2014). "Since non-coding RNAs and pseudogenes are now recognized to be important in physiology and disease, we investigated HMGA1 pseudogenes in cancer settings using bioinformatics analysis." (PMID 25268743, 2014). "HMGA1 is overexpressed in all aggressive cancers studied to date, and high levels portend a poor prognosis in diverse tumors." (PMID 23658826, 2013). "It will be of great interest to understand the role of let-7b/HMGA1 interaction for the development of cancer stem cells in context with the regulation of others potential target genes of the let-7 family members." (PMID 23798998, 2013). "A mechanism of transcriptional regulation of the human HMGA1 gene has been postulated before both in embryonic and cancer cells highly expressing HMGA1." (PMID 24367622, 2013). "Several studies have reported that HMGA1 expression is elevated in a variety of human cancers, including carcinomas derived from thyroid, prostate, colon and breast tissues." (PMID 23945276, 2013). "On the other hand, suppression of let-7b in these cancer cells resulted in an up-regulation of HMGA1 up to 168.6%." (PMID 23798998, 2013). "HMGA1 expression is highest in cultured cells that are derived from poorly differentiated cancers, including breast, prostate, pancreatic, uterine, colon, and lung cancers as compared to cell lines from more differentiated tumors." (PMID 23166588, 2012). "HMGA1 expression is enriched in hESCs and fully reprogrammed iPSCs, with intermediate levels in cancer cells and lower levels in differentiated fibroblasts, 2)." (PMID 23166588, 2012). "The high mobility group A1 (HMGA1) gene is highly expressed in hESCs and poorly differentiated, stem-like cancers; however, its role in these settings has been unclear." (PMID 23166588, 2012). "Because prior studies demonstrate that cancers with stem-like molecular signatures have poor outcomes, it is likely that HMGA1 drives a refractory, advanced tumor by inducing these pathways in tumor cells." (PMID 22053823, 2011). "Although the high mobility group A1 (HMGA1) gene is widely overexpressed in diverse cancers and portends a poor prognosis in some tumors, the molecular mechanisms that mediate its role in transformation have remained elusive." (PMID 22053823, 2011). "We found that HMGA1 induces inflammatory pathways early in lymphoid tumorigenesis and pathways involved in stem cells, cell cycle progression, and cancer in established tumors." (PMID 22053823, 2011).
cancer (continued). "Given the recent evidence that inflammation is a precursor lesion in some cancers, this link between HMGA1, NFκB, and inflammation are consistent with a model whereby these proteins cooperate to induce inflammatory signals and drive transformation." (PMID 22053823, 2011). "Expression of HMGA1 and 8 other transcriptional regulators predicted poor survival in these cancers." (PMID 22053823, 2011). "More recently, HMGA1 was identified as a key transcription factor enriched in embryonic stem cells and poorly differentiated cancers of the breast, bladder, and brain." (PMID 22053823, 2011). "In established tumors, HMGA1 induced pathways involved in cell cycle progression, cell-mediated immune response, and cancer." (PMID 22053823, 2011). "The HMGA1 proteins are well known to play a significant role in the pathogenesis of various diseases including cancer." (PMID 18651940, 2008). "Moreover, compared to the control group, the proportion of 231RR cells undergoing apoptosis after IR treatment was significantly increased in the HMGA1 knockdown group, which suggested that HMGA1 is involved in the resistance of cancer cells to IR exposure." (PMID 40288645, 2025). "Mechanistically, LUCAT1 could significantly up-regulate HMGA1 expression, a key regulatory genes of cancer stem cell, and inhibition of malignant phenotypes in BC cells by silencing LUCAT1 was reversed by overexpression of HMGA1." (PMID 40025525, 2025). "In contrast, HMGA1 is expressed at very high levels in many different types of human cancer cells." (PMID 41183073, 2025). "In sharp contrast, HMGA1 is overexpressed at very high levels in many kinds of human cancer cells." (PMID 41183073, 2025). "Our work identifies HMGA1 as a key driver of cancer aggression and suggests that measuring its levels could help predict patient outcomes and guide more effective treatment strategies, particularly for immunotherapy." (PMID 41463532, 2025). "Among these, NAT1, BIRC3, EZH2, MAD2L1, ATP2A3, HMGA1, and BST2 are known cancer-associated genes." (PMID 41255601, 2025). "This synergistic relationship between chromatin remodeling and RNA modification could represent a powerful, self-reinforcing circuit that amplifies oncogenic transcriptional programs and contributes to the pervasive influence of HMGA1 across cancer hallmarks." (PMID 41463532, 2025). "For example, transgenic mice overexpressing Hmga1 in lymphoid cells develop clonal expansion with evolution to leukemia by upregulating transcriptional networks active in proliferating stem cells, poorly differentiated cancer cells, and inflammation." (PMID 39895630, 2025). "While the specific cellular expression patterns showed context-dependence such as prominent expression in malignant cells and fibroblasts in ESCA the consistent association with immunosuppressive elements firmly establishes HMGA1 as a conserved immune modulator across cancers." (PMID 41463532, 2025). "Hmga1 remodels chromatin to drive developmental transcriptional networks in cancer." (PMID 40182023, 2025). "Furthermore, IGF2BP2 expression positively correlated with LUCAT1, HMGA1 and cancer stem cell markers expression in BC cells." (PMID 40025525, 2025). "Finally, pan‐cancer analysis revealed that HMGA1 is significantly upregulated across a broad range of tumour types compared to corresponding normal tissues, highlighting its potential as an oncogenic driver in various malignancies." (PMID 40988131, 2025). "In addition, overexpression of HMGA1 in human and murine cancer cells promotes colony formation and invasion and metastasis of cancer cells." (PMID 38383528, 2024). "Studies have shown that HMGA1 is involved in chemoresistance to platinum-based drugs (cisplatin), imatinib, 5-fluorouracil (5-FU), methotrexate, gemcitabine, and cyclophosphamide in various cancers 59-68." (PMID 38725843, 2024). "HMGA1 is frequently overexpressed in aggressive and advanced-stage malignant tumors." (PMID 38725843, 2024).
cancer (continued). "The transcriptional regulation of SLC7A11 is highly compatible with the mechanism of action of HMGA1, suggesting that HMGA1 may regulate SLC7A11 at the transcriptional level to achieve cancer cells’ resistance to ferroptosis." (PMID 38383528, 2024). "In this study, we discovered that HMGA1 undergoes PARylation in response to DNA damage, which promotes Ku protein recruitment and activates DNA‐PKcs, thereby enhancing DNA repair and reducing cancer cell sensitivity to the PARP inhibitor olaparib." (PMID 39690136, 2024). "HMGA1 is an abundant non-histone chromatin protein that has been implicated in embryonic development, cancer, and cellular senescence, but its specific role remains elusive." (PMID 39134516, 2024). "Thus, inhibition of HMGA1 enhances the sensitivity of cancer cells to DDP through upregulating lipid peroxidation-induced ferroptosis." (PMID 38383528, 2024). "Previous studies have shown that HMGA1 can promote the binding of EZH2 to cancer cell DNA, promote the formation of cytoplasmic chromatin fragments (CCF), and activate the cGAS-STING pathway, which can promote the production of inflammatory factors and the metastasis of BC." (PMID 37858183, 2023). "It is also possible that HMGA1 activates the expression of mitotic spindle assembly checkpoint-related genes, which is an important control system of cell cycle, leading to checkpoint damage and chromosome instability and promoting the progression of cancer." (PMID 37240870, 2023). "HMGA1 remodels chromatin structure and participates in multiple fundamental cellular processes, including cell proliferation, differentiation, apoptosis, DNA repair, and cancer development." (PMID 37240870, 2023). "In summary, we provided a promising circRNA-targeted therapy for GC patients, in which the circ_002136/miR-16-5p/HMGA1 axis might provide a new idea for cancer treatment." (PMID 36760722, 2023). "Moreover, high expression of HMGA1 and FOXM1 was associated with a poor prognosis in the overall cancers." (PMID 37240870, 2023). "CD44 and HMGA1 are well-known markers of cancer stem cells (CSCs)." (PMID 37858183, 2023). "However, the role of abnormally high level of HMGA1 in cancer cells and its regulatory mechanism still require further investigation." (PMID 37240870, 2023). "High mobility group A1 (HMGA1) chromatin regulators are upregulated in diverse tumors where they portend adverse outcomes, although how they function in cancer remains unclear." (PMID 36919699, 2023). "Recently the role of HMGA1 expression in BC cells has been thoroughly investigated showing that HMGA1 influences the expression of a plethora of factors inserted in different pathways involved in cancer onset and development." (PMID 36614035, 2022). "HMGA1 influences the epigenetic status of cancer cells in multiple ways." (PMID 36614035, 2022). "Epigenetic changes through GPG methylation of HMGA1 may regulate its gene expression in various cancers." (PMID 35864955, 2022). "Similarly, HMGA1 depletion increases autophagy and finally influences cancer cell viability by inhibiting the mTOR pathway and upregulating the transcription level of ULK1." (PMID 35864955, 2022). "Moreover, HMGA1 protein-targeted therapies based on aptamers or antisense RNA, as well as HMGA1 gene inhibitors, were developed to slow down the proliferation of cancer cells or to increase their sensitivity to chemotherapy." (PMID 35805937, 2022). "Therefore, our findings provide new insight into HMGA1-mediated immune function and further broaden the oncogenic roles of HMGA1 in cancers." (PMID 35785026, 2022). "HMGA1 promotes tumor initiation, cancer stemness and metastasis in TNBC." (PMID 35611554, 2022). "A large number of studies have shown that HMGA1 participates in the regulation of cancer diseases." (PMID 35864955, 2022). "LINC00665 directly binds to the HMGA1 protein to promote cancer cell growth and invasion." (PMID 35864955, 2022).